PIM1 (Pim-1 proto-oncogene, serine/threonine kinase)
Diseases named in the same sentence as PIM1 in open-access papers (continued):
Sharing a sentence is not in itself a finding about the gene and the disease.
bladder cancer (continued). "Moreover, upregulation of Pim-1 in invasive bladder cancer compared with Non-invasive tumors indicated that Pim-1 also may also contribute to bladder cancer progression." (PMID 21143989, 2010). "However, the expression and significance of Pim-1 in bladder cancer remains unknown." (PMID 21143989, 2010).
chronic lymphocytic leukemia (4 papers, 2014 to 2021). "Similarly, an association between PIM1 and CXCR4 could also be seen in chronic lymphocytic leukemia." (PMID 34503111, 2021). "One of the most promising PIM inhibitors (PIMi) was SGI-1776, a compound with activity against PIM1, PIM2 and PIM3 at nanomolar concentrations, which induced apoptosis at micromolar doses in chronic lymphocytic leukemia, mantle cell lymphoma, and acute myeloid leukemia." (PMID 25386922, 2014).
chronic myeloid leukemia (4 papers, 2022 to 2024). "Notably, one chronic myeloid leukaemia cell line, K-562, was included in some preliminary experiments of this study, considering its higher expression of PIM1." (PMID 36831387, 2023).
coronary artery disease (4 papers, 2014 to 2023). "PIM1 has been implicated in vascular smooth muscle cell proliferation in atherosclerotic plaques and is strongly upregulated in coronary artery disease." (PMID 37428809, 2023). "To further investigate the involvement of Pim-1 in clinical settings, we measured its protein expression in the right atrial appendage samples of diabetic and non-diabetic patients undergoing coronary artery bypass graft surgery for ischemic heart disease." (PMID 24685144, 2014). "Success of PIM1 delivery and integration into mCPCs in vitro and cardiomyocytes in vivo by MC highlights the possibility of a non-cell based therapeutic approach for treatment of ischemic heart disease and MI." (PMID 28323876, 2017).
COVID-19 (4 papers, 2022 to 2024). A disease caused by infection with severe acute respiratory syndrome coronavirus 2. "The expression of HSC proliferation genes, such as PIM1, was increased in the COVID-19 group when compared to the healthy population." (PMID 37446049, 2023). "Both CUN and COV groups, compared with their respective control group, expressed higher level of genes involved in the antiviral response and proliferation, like IFIT5, IFI27 and PIM1, suggesting that those cells could have been activated by SARS-CoV-2 infection." (PMID 35710943, 2022). "This study aimed to evaluate the antiviral activity of 2-pyridone PIM1 inhibitor against SARS-CoV-2 and its potential role in hindering the progression of COVID-19." (PMID 37211584, 2023). "Hence, the ability of 2-pyridone PIM1 inhibitor to normalize the expression of Notch 1 and reduce the expression of Notch 2 below the control levels could provide a mechanism by which 2-pyridone PIM1 inhibitor could be effective in treatment of COVID-19." (PMID 37211584, 2023).
diabetic cardiomyopathy (4 papers, 2014 to 2024). Diabetic cardiomyopathy is a disorder of the heart muscle in people with diabetes. "Importantly, restoring the Pim-1 levels by systemic adeno-associated viral vector gene delivery halted the progression of diabetic cardiomyopathy." (PMID 24685144, 2014). "Similarly, miR-410-5p is involved in the development of diabetic cardiomyopathy and regulates cardiomyocyte apoptosis by targeting PIM1 protein and its downstream protein Bcl-2/Bax." (PMID 38361743, 2024). "On the contrary, forced expression of Pim-1 would be beneficial for curing diabetic cardiomyopathy." (PMID 29179437, 2017). "Finally, we applied a rescue approach which demonstrates for the first time the importance of Pim-1 in gender disparity of diabetic cardiomyopathy." (PMID 24685144, 2014).
follicular lymphoma (4 papers, 2021 to 2025). Follicular lymphoma is a form of non-Hodgkin lymphoma characterized by a proliferation of B cells whose nodular structure of follicular architecture is preserved. "Indeed, structural variants of MYC are largely absent in samples from a Follicular Lymphoma cohort where PIM1 variants are enriched." (PMID 41152984, 2025). "Of these, mutations in CREBBP, KMT2D, TNFRSF14 and RRAGC were enriched in follicular lymphoma, and those of BTG2, HLA-A, PIM1, IGLL5, SOCS1, CD83 and SGK1 were enriched in DLBCL." (PMID 33945543, 2021). "As expected, mutations in frequent drivers such as CREBBP, KMT2D,TNFRSF14 and RRAGC were more frequent among follicular lymphomas, those of MYC, CCND3 and ID3 prevailed among Burkitt lymphoma and those of BTG2, PIM1, SGK1 and SOCS1 were more frequent among DLBCL." (PMID 33945543, 2021).
head and neck squamous cell carcinoma (4 papers, 2011 to 2022). A squamous cell carcinoma that arises from any of the following anatomic sites: lip and oral cavity, nasal cavity, paranasal sinuses, pharynx, larynx, and salivary glands. "There are no studies that have analyzed the response to radiotherapy in patients with head and neck squamous cell carcinoma (HNSCC) according to the expression of PIM-1." (PMID 34993612, 2022). "Stimulation of the EGFR pathway with EGF or TGF-α induced PIM-1 upregulation and nuclear translocation in head and neck squamous cell carcinoma (HNSCC) cell lines." (PMID 27596051, 2016).
heart failure (4 papers, 2012 to 2023). Inability of the heart to pump blood at an adequate rate to meet tissue metabolic requirements. "Decreased telomere length is a hallmark of heart failure due to cells entering senescence; therefore, Pim-1 plays a protective role in cardiomyocytes." (PMID 37511341, 2023). "It has also been demonstrated that Pim-1 expression in cardiomyocytes is upregulated in vivo, with increased Pim-1 expression observed in heart tissue sampled from patients with heart failure." (PMID 37511341, 2023). "Regenerative therapies utilizing stem/progenitors cells engineered with Pim-1 enhanced regenerative potential of the cells, thus making Pim-1 an important player in the treatment of severe heart failure." (PMID 27103465, 2016). "Revealing these underlying mechanisms of telomere preservation and acceleration of mitosis by Pim-1 offers exciting new potential therapeutic interventions for CPC-mediated cardiac regeneration in heart failure." (PMID 22915504, 2012). "Understanding the molecular basis for Pim-1 enhancement of CPC activity is essential to delineate the mechanistic basis of Pim-1 activity and determine the potential of Pim-1-modified CPCs for incorporation into protocols for augmented clinical treatment of heart failure." (PMID 22915504, 2012).
liver cancer (4 papers, 2016 to 2024). An epithelial or non-epithelial malignant neoplasm that arises from the liver. "To validate the relationship between miR24‐2 and Pim1, we detected the expression of miR24‐2 and Pim1 in the patients of liver cancer." (PMID 32030886, 2020). "Collectively, these findings suggest that Pim1 determines the oncogenic functions of miR24‐2 in human liver cancer." (PMID 32030886, 2020). "Herein, our observations suggest both miR24‐2 and Pim1 are up‐regulated in human liver cancers, and miR24‐2 accelerates growth of liver cancer cells in vitro and in vivo." (PMID 32030886, 2020). "Collectively, these observations suggest both miR24‐2 and Pim1 or Src are up‐regulated in human liver cancers." (PMID 32030886, 2020). "In this study, we indicate that miR24‐2 and Pim1 are up‐regulated in human liver cancers, and miR24‐2 accelerates growth of liver cancer cells in vitro and in vivo." (PMID 32030886, 2020). "Collectively, these observations suggest that miR24‐2 increases the expression of Pim1 dependent on the modification of H3K9me3 in liver cancer cells." (PMID 32030886, 2020). "Notably, our findings suggest that miR24‐2 alters several related genes (pHistone H3, SUZ12, SUV39H1, Nanog, MEKK4, pTyr) and accelerates progression of liver cancer cells through Pim1 activation." (PMID 32030886, 2020). "Given that miR24‐2 enhances the expression of Pim1, we consider to identify whether Pim1 is required for the oncogenic action of miR24‐2 in liver cancer cells." (PMID 32030886, 2020). "In particular, Pim1 is required for the oncogenic action of miR24‐2 in liver cancer." (PMID 32030886, 2020). "Moreover, there was a strong positive relevance between miR24‐2 and Pim1 or Src in human liver cancer." (PMID 32030886, 2020). "Our previous studies showed that H19 enhanced Pim1 expression and function in the liver cancer." (PMID 27167190, 2016). "Moreover, oncogene Pim1 is required for the oncogenic action of miR24‐2 in human liver cancer." (PMID 32030886, 2020). "Taken together, both Pim1 and P21(WAF1/Cip1) determine oncogenic function of JMJD2A in liver cancer cells." (PMID 28467776, 2017). "Western blotting with anti‐Pim1 showed that the expression of Pim1 was significantly increased in liver cancer tissues compared to their adjacent noncancerous tissues [96.83% (61/63), n = 63, P < .01]." (PMID 32030886, 2020). "The Pim1 mRNA was significantly increased in liver cancer tissues compared to their adjacent noncancerous tissues [96.83% (61/63), n = 63, P < .01]." (PMID 32030886, 2020).
lupus nephritis (4 papers, 2019 to 2024). Glomerulonephritis in the context of systemic lupus erythematosus. "More specific to kidney research, PIM1 is aberrantly overexpressed in renal cell carcinoma and lupus nephritis." (PMID 33933144, 2021).
lymph node metastasis (4 papers, 2012 to 2022). "Additionally, the positive expression of OPN, αvβ3 and Pim-1 in NSCLCs was associated with an increase in pathological grade, lymph node metastasis and advanced clinical stage (all P<0.01)." (PMID 23119061, 2012). "We found that Pim-1 protein was frequently upregulated in lung tumor tissues, and its expression was closely related to advanced stage and lymph node metastasis of NSCLC." (PMID 25342548, 2014).
pancreatic ductal adenocarcinoma (4 papers, 2014 to 2021). An infiltrating adenocarcinoma that arises from the epithelial cells of the pancreas. "For example, in pancreatic ductal adenocarcinoma cells, under hypoxic stress, HuR stabilizes the mRNA of a hypoxia-inducible and pro-oncogenic kinase PIM1, resulting in its protein overexpression, thereby promoting tumor cells growth." (PMID 34400891, 2021).
Sepsis (4 papers, 2020 to 2025). Sepsis is defined as life-threatening organ dysfunction caused by a dysregulated host response to infection. "Furthermore, silencing miRNA‐195 by gene KO can increase the expression of certain proteins—BCL‐2, Sirt1 and Pim‐1—and significantly reduce the potential trans‐organ damage associated with sepsis." (PMID 38014923, 2024). "The expression of PIM1 was significantly elevated on CD4+ T cells from sepsis patients and was correlated with both SOFA and APACHE II scores." (PMID 40899834, 2025). "We first identified the proviral integration site for Moloney murine leukemia virus 1 (PIM1) as a significantly upregulated gene in CD4+ T cells from sepsis patients by conducting a comprehensive transcriptome meta-analysis." (PMID 40899834, 2025). "The section that follows will provide additional evidence of the critical role played by PIM1 in sepsis, suggesting its potential involvement in the immunosuppressive mechanisms of the disease." (PMID 39108261, 2024). "Key diagnostic biomarkers, including PIM1, HIST1H1C, and IGSF6, have been identified and incorporated into an accurate riskScore model for the prognosis of sepsis." (PMID 39108261, 2024). "The role of PIM1 in modulating the immune-inflammatory response during sepsis was further confirmed through experimental validation, suggesting its potential as a therapeutic target." (PMID 39108261, 2024). "Our study provides evidence that PIM1 serves as a crucial regulator of sepsis-induced inflammation and elucidates that PIM1 participates in regulating the imbalance of Th1, Th17, and Treg subsets, further promoting inflammatory and anti-inflammatory imbalance in sepsis." (PMID 40899834, 2025). "These experimental findings were consistent with the conclusions of our previous bioinformatics analysis, confirming that PIM1 may be one of the critical genes involved in the immune suppression observed following the onset of sepsis." (PMID 39108261, 2024). "We found that LUADT1 was downregulated in sepsis and might regulate the miR-195/Pim-1 axis to inhibit LPS-induced of HCAEC apoptosis." (PMID 33225891, 2020). "The results showed that the expression levels of LUADT1 were significantly and inversely correlated with the expression levels of miR-195 in sepsis patients (R2 = 0.0699, p < 0.05), while the expression levels of Pim-1 were positively correlated with that of LUADT1 (R2 = 0.1412, p < 0.05)." (PMID 33225891, 2020). "In conclusion, LUADT1 is downregulated in sepsis and may regulate the miR-195/Pim-1 axis to inhibit the apoptosis of HCAECs induced by LPS." (PMID 33225891, 2020). "In summary, LUADT1 may protect cardiac endothelial cells against apoptosis in sepsis by regulating the miR-195/Pim-1 axis." (PMID 33225891, 2020).
uveitis (4 papers, 2022 to 2024). An inflammatory process affecting a part of or the entire uvea. "Considering the role of Pim1 in regulating T cell differentiation, DMF may reverse the Teff/Treg cell imbalance by regulating Pim1 during uveitis." (PMID 38684986, 2024). "Importantly, the upregulation of PIM1 and its regulatory function were conserved in a human uveitis, VKH." (PMID 36195600, 2022). "To investigate whether the upregulation of PIM1 expression is conserved in human uveitis, we generated scRNA-seq data from peripheral blood mononuclear cells (PBMC) obtained from six patients with VKH and six healthy controls (HC)." (PMID 36195600, 2022). "Collectively, a dynamic immune cellular atlas during uveitis is developed and implicate that PIM1 may be a potential therapeutic target for VKH." (PMID 36195600, 2022). "Thus, DMF treatment could inhibit ocular infiltration of Teff cells in uveitis and this effect might depend on its inhibition of PIM1 and CXCR4 expression." (PMID 38684986, 2024). "Here the authors use scRNA sequencing in mouse experimental autoimmune uveitis (EAU) and show PIM1 promotes the imbalance of Th17 and Treg cells, and find elevated PIM-1 in human uveitis disease." (PMID 36195600, 2022). "Therefore, PIM1 may act as a potential therapeutic target for uveitis." (PMID 36195600, 2022). "In addition, human uveitis, Vogt−Koyanagi−Harada disease (VKH), is characterized by the overexpression of PIM1 in CD4+ T cells and plasma cells, and PIM1 inhibition decreases the expansion of CD4+ T and B cells." (PMID 39372407, 2024). "Analysis of the scRNA-seq data indicated that inhibition of PIM1 and CXCR4 might be the critical beneficial mechanism of DMF in uveitis." (PMID 38684986, 2024). "To explore the impact of DMF on ocular T cell infiltration during uveitis, we integrated retinal immune cells of EAU mice with CDLN cells from each group and observed that T cells in the retina of EAU mice expressed the highest level of Cxcr4 and Pim1." (PMID 38684986, 2024). "Importantly, the upregulation of PIM1 in CD4+ T cells and plasma cells is conserved in a human uveitis, Vogt-Koyanagi-Harada disease (VKH), and inhibition of PIM1 reduces CD4+ T and B cell expansion." (PMID 36195600, 2022). "Furthermore, our study verifies the upregulation of PIM1 in CD4+ T cells and PCs in a human uveitis, Vogt-Koyanagi-Harada disease (VKH)." (PMID 36195600, 2022). "Therefore, our study indicated that PIM1 and CXCR4 might be critical mediators of the effects of DMF in uveitis." (PMID 38684986, 2024). "Therefore, the abnormal Id2/Pim1 pathway in EAU might contribute to Th17 cell differentiation and pathogenicity in uveitis, which could be ameliorated by Id2 inhibition." (PMID 37344856, 2023). "Therefore, increased PIM1 expression and potential therapeutic value of targeting PIM1 may not be limited to uveitis but may also be applied to other CNS autoimmune diseases, such as MS." (PMID 36195600, 2022).
autoimmune uveitis (3 papers, 2022 to 2024). An autoimmune form of uveitis (disease). "Herein, by performing single-cell RNA sequencing (scRNA-seq) on experimental autoimmune uveitis (EAU), we identify disease-associated alterations in cell composition and transcriptional regulation as the disease progressed, as well as a disease-related molecule, PIM1." (PMID 36195600, 2022).
Burkitt lymphoma (3 papers, 2014 to 2021). A rare form of malignant mature B-cell non-Hodgkin lymphoma. "Our co-immunoprecipitation experiments in EBNA3C expressing Burkitt's lymphoma cells and EBV transformed Lymphoblastoid cells also demonstrated that Pim-1 forms a strong molecular complex with EBNA3C in infected cells." (PMID 25121590, 2014).
colitis (3 papers, 2020 to 2023). Inflammation of the colon. "For example, there was significant induction of Traf1, Tnfrsf9, Hif1a, Slc2a1 and Pim1 in TREG clusters in CPI colitis in comparison with TREG clusters in control mice." (PMID 37872166, 2023). "In a DSS-induced colitis mouse model, PIM1 expression was increased in colon tissue and correlated with mucosal inflammation." (PMID 36429128, 2022). "PIM-1, one of the three PIM kinases, is significantly induced by cigarette smoke in RAW 264.7 cells, and the inhibition of PIM-1 in a dextran sodium sulfate colitis mice model improved colitis by reducing the excessive activity of macrophages and the immune response of Th1 and Th17." (PMID 32698512, 2020).
esophageal squamous cell carcinoma (3 papers, 2014 to 2023). Esophageal squamous cell carcinoma (ESCC) is a type of esophageal carcinoma (EC) that can affect any part of the esophagus, but is usually located in the upper or middle third. "Another study established that alpinumisoflavone induces apoptosis via modulating miR-370/PIM1 signaling in esophageal squamous cell carcinoma." (PMID 37507864, 2023).
hepatoblastoma (3 papers, 2012 to 2021). Hepatoblastoma (HB) is a malignant hepatic tumor and is the most common pediatric liver cancer. "To this end, we monitored PIM1 mRNA levels in serum-starved HeLa (human cervical adenocarcinoma), HepG2 (human hepatoblastoma), and MDA-MB-231 (human breast adenocarcinoma) cells, then measured changes in PIM1 mRNA expression as a function of time following mitogenic stimulation using serum+TPA." (PMID 22413002, 2012). "The expression of PIM kinases (PIM1, PIM2, and PIM3) was evaluated in the long-term passaged human hepatoblastoma cell line, HuH6, and the human hepatoblastoma PDX cell line, COA67, by immunoblotting." (PMID 29854306, 2018). "We preliminarily showed that knockdown of PIM1 or PIM2 did not affect hepatoblastoma cell proliferation." (PMID 29854306, 2018).